RB1 (RB transcriptional corepressor 1)
Diseases named in the same sentence as RB1 in open-access papers (continued):
Sharing a sentence is not in itself a finding about the gene and the disease.
cancer (continued). "Only cancer cases presented RB1 promoter methylation in the presence of HPV and EBV (33.3%)." (PMID 26032781, 2015). "In addition to its well-established importance in development and cancer research, special attention has been paid to the role of Rb1 in tissue regeneration, particularly auditory HC regeneration." (PMID 25755634, 2015). "However, our results showed an expressive correlation between RB1 methylation and cancer samples (p = 0.009)." (PMID 26032781, 2015). "Therefore, many efforts have been dedicated to investigate RB1 mechanisms of action in order to shed light on key events in cancer development." (PMID 26160835, 2015). "Similarly, another approach took advantage of deregulated E2F transcriptional activity to activate a prodrug selectively in cancer cells with inactive RB1." (PMID 26160835, 2015). "Of note, the CCND1 and CDKN2A loci show some of the highest frequencies of amplification and deletion rates seen in SCCHN and several other cancer types; this further supports the idea that it may be important to restrain RB1 function post-translationally." (PMID 26265441, 2015). "Two main strategies have been conceived to directly target RB1 for cancer treatment." (PMID 26160835, 2015). "CDK2 and CCNE1 were increased in carcinomas showing that these use the opposite way to control RB1." (PMID 26008974, 2015). "Indeed, no clear-cut correlation has been defined between distinct 13q deleted genes and cancer, in addition to RB1 in Rb." (PMID 24433316, 2014). "This is the first report of chromothripsis as a mechanism for RB1 gene inactivation in cancer." (PMID 24509483, 2014). "Since disruption of the RB1/E2F pathway and upregulation of E2F target genes is frequently observed in human cancers upregulation of (a subset) of FA genes may be a common feature for tumors with a disrupted RB1 pathway." (PMID 25161863, 2014). "It is possible that this increased sensitivity was due to the effect of acute inactivation of RB1, whereas established RB1 null cancer cells, used here, have adapted other mechanisms for DNA repair and apoptosis evasion, or have rewired to compensate for RB loss through activation of p107." (PMID 24265703, 2013). "The stratification of these patients by profiling p16INK4and RB1 protein expression in the tumors might provide predictive biomarkers for cancer prognosis." (PMID 22619677, 2012). "The significance of increased expression of functionally intact tumor suppressor proteins such as p16 and RB1 in malignant cells remains poorly understood but might be explained by the concept of the cellular homeostasis in the cancer cells." (PMID 22619677, 2012). "The CCND1/CDKN2A assay predicted 5% (1/20) as RB1 (-) cancers." (PMID 21447152, 2011). "Clinically, RB occurs in two forms; a unilateral form that corresponds to 90% of non-inheritable (sporadic) RB, and a bilateral form that is inheritable or germinal, exemplifying the classical cases of a cancer with an inheritable genetic anomaly of tumour suppressor gene RB1." (PMID 21545722, 2011). "An inverse correlation of CDKN2A and RB1 expressions has been reported in several types of cancers." (PMID 21447152, 2011). "Thus, it can be concluded that LIMD1 is a susceptible gene for HNSCC development and its alterations, alone or with RB1 alterations acts as an important prognostic marker in this cancer." (PMID 20226061, 2010). "Furthermore, the canonical cancer gene RB1 and the CDKN2A/B locus are present in two of its co-lost regions." (PMID 20052266, 2010).
cancer (continued). "We hypothesise that this reduction entails that the E2F inhibitor RB1 is titrated out and that the G1/S-transition checkpoint consequently is overridden, enabling the cancer cells to proliferate." (PMID 19156145, 2009). "Indeed, the retinoblastoma gene RB1 was the first hereditary cancer gene and the first tumor-suppressor gene to be cloned, and it has proven to be biologically important." (PMID 16231982, 2005). "Moreover, 6MP IC50 tends to be lower in RB1–NUDT15 deleted cells in the majority of cancer types and reached statistical significance in the combined cell lines, indicating that RB1‐deleted tumors may be treatable via collateral lethality." (PMID 40904703, 2025). "Indeed, co‐occurrence of NUDT15 and RB1 deep deletion is commonly observed in multiple cancer types according to the TCGA database, and nearly all patients with deep/shallow RB1 deletion also carry NUDT15 deletion across cancer types, which is induced by the extensive deletion event at this locus." (PMID 40904703, 2025). "However, no mutations in the RB1 gene or other cancer predisposition genes were identified through whole blood whole‐exome sequencing analysis." (PMID 41307228, 2025). "We found that MCF7CCNE1amplified cells were more sensitive to SKP2 inhibition when compared to parental MCF7 cells, corroborating the hypothesis that RBness cancers harbor synthetic lethal targeting opportunities similar to those found in RB1-defective cancers." (PMID 40138429, 2025). "Comprehensive next‐generation sequencing (NGS) and Sanger sequencing did not reveal any pathogenic variants in RB1 or other cancer predisposition genes, suggesting that the sequential cancers were likely driven by treatment‐related mutagenesis rather than inherited genetic factors." (PMID 41307228, 2025). "This might be influenced by the specific molecular context of the cancer rather than being a universal feature of RB1 loss." (PMID 40138429, 2025). "Similarly, RB1/RBL1/RBL2 can be deleted in cancers, which leads to increased E2F activity." (PMID 38678032, 2024). "Despite the initial heightened sensitivity of RB1-deficient malignancies to DNA damage, strategies involving combinations of DNA-damaging agents with inhibitors of DNA damage repair, such as poly-ADP ribose polymerase (PARP) inhibitors (PARPis), show promise in addressing RB1-deficient cancers." (PMID 38672640, 2024). "We hypothesize that those MYC amplification cancer cells may undergo RB1 loss in mRNA or protein level without RB1 deletion." (PMID 38424044, 2024). "Moreover, defects in mitotic progression arising from NFYC-AS1 depletion may create new vulnerabilities, which can be particularly deleterious in RB1-defective cancers, as already shown for Aurora B kinase inhibitors." (PMID 38467619, 2024).
cancer (continued). "This is evidence that in RB1-mutant cancers, NNMT is not directly down-regulated by loss of Rb." (PMID 37883365, 2023). "Thus, reactivating nonsense mutant RB1 in such patients could be a promising strategy for improved cancer treatment." (PMID 37917619, 2023). "Insertion of Alu elements into DNA repair genes such as breast cancer 1 genes (BRCA1) and 2 (BRCA2), LINE-1 retrotransposon into tumor suppressor gene adenomatous polyposis coli (APC), and retinoblastoma 1 (RB1) gene cause disruption in the function of these genes, thus leading to tumorogenesis." (PMID 35887150, 2022). "Moreover, the association of these mutations with the clinical outcome of patients with cancer is not well established, thus further complicating the role of Rb1 in cancer." (PMID 35267571, 2022). "For example, the fraction of cancers exhibiting gene deletions versus other genetic alterations is generally higher for RB1 than for RBL1 or RBL2, suggesting selective pressure may favor complete functional inactivation of RB1 alleles." (PMID 35368709, 2022). "Notably, recent studies have found that RB1 deficiency can predict drug resistance and sensitivity in triple-negative breast, pancreatic, and prostate cancers." (PMID 35299734, 2022). "In addition, RB1 is a tumor suppressor gene and plays significant role in cancer biology." (PMID 33943042, 2021). "Furthermore, targeted sequencing with cancer‐related genes revealed the relationships between the altered gene and metastatic sites, age, gender, smoking, etc.,16, 17 and alterations in GNAS and RB1 were reported to be associated with disease recurrence." (PMID 33455072, 2021). "RB1 mutation could be acquired, albeit at a lower rate (~5%), after exposure to CDK4/6i in the clinical setting, establishing a feedback loop by which cancer cells evade cell cycle checkpoint inhibition." (PMID 34508104, 2021). "Therefore, RB1 is frequently reported to be downregulated in many types of human cancers." (PMID 34336665, 2021). "Thus, MLN4924 is a promising approach to exploit the SKP2-dependency of RB1 null cancers." (PMID 32123578, 2020). "Inhibition of MYCNOS1 expression may be necessary to suppress MYCN activity when treating MYCN-amplified cancers without RB1 mutation." (PMID 33270844, 2020). "Thus, cdk4, cdk6, e2f1, and rb1 not only participate in the progression of cancer cells but might also be useful biomarkers for predicting prognosis in some tumors." (PMID 32357912, 2020). "In addition, the interaction between RB1 and miRNAs were also investigated in human cancers." (PMID 32013999, 2020).
cancer (continued). "Since abnormal cells, including cancer cells, are under various cellular stresses such as oxidative stress, nutrient stress, and osmotic stress, we speculate that regulation of the RB1-mediated cell cycle by Rbfox2 could play a role in disease development and cancer progression." (PMID 28894257, 2017). "Moreover, the data demonstrate fundamental differences in p16/RB1 pathway mediated control of epithelial versus fibroblast cell growth highlighting the importance of defining p16 functions in epithelial cells that give rise to cancer." (PMID 28414317, 2017). "Indeed in cancer cells lacking RB1, the E2F1-mediated apoptosis resulting from RB1 deficiency is suppressed through resistance mechanisms." (PMID 26160835, 2015). "Furthermore, unleashing RB1 oncosuppressive potential is an appealing strategy for cancer therapy." (PMID 26160835, 2015). "In this study we monitored expression of 14 FA genes during the cell cycle and in cancers with a disrupted RB1/E2F pathway, in an attempt to identify gene expression patterns that characterize two important interconnected pathways, i.e. the FA and RB1/E2F pathways." (PMID 25161863, 2014). "Thus, in some cellular contexts, inactivation of the RB1 gene could lead to chromosome instability (CIN), allowing secondary and tertiary mutations in key cancer pathways to be rapidly acquired." (PMID 23765217, 2013). "RB1 mediates the proliferation block induced by a range of DNA damaging agents and cells with RB1 loss show accelerated death following DNA damage, suggesting that inhibition of radiation-mediated RB1 activation could be a strategy for radio-sensitization of RB1 positive cancers." (PMID 22384045, 2012). "The RB1 gene was first identified based on its mutation in retinoblastoma, however, it has since been found to be absent or misregulated in almost all human cancers." (PMID 20298605, 2010). "While CDKN2A deletions were enriched in RBness cancers, conversely, amplifications in CDKN2A were enriched in RB1-defective cancers." (PMID 40138429, 2025). "Not surprisingly, both shallow (referring to heterozygous) and deep deletions result in enrichment of the RB pathway and decreased expression of RB1, which can be validated in other cancer types from TCGA." (PMID 40904703, 2025). "Consistently, a significant association between NUDT15 deletion and poor survival was also observed in other cancer types (e.g., UCEC), with a similar pattern of RB1 deletion." (PMID 40904703, 2025). "Consistently, we found that genetic RB1 knockout (RB1-KO) via CRISPR-Cas9 indeed increased the abundance of P16 in MGC803 and ECA109 cancer cells, whereas transient GFP-RB1 overexpression (RB1-OE) significantly decreased the abundance of P16." (PMID 39351198, 2024).
cancer (continued). "Here, the authors show that MYC amplification induces CDK4/6 inhibitors resistance through transcriptional regulation of KLHL42, leading to RB1 degradation and targeting MYC overcomes CDK4/6 resistance in preclinical cancer models." (PMID 38424044, 2024). "Instead, we consistently observed a significant difference in the abundance of the RB1 protein between these cancer cell lines with and without gain or loss of P16 function, indicating that there is a cell-specific posttranscriptional mechanism of P16 loss-mediated RB1 upregulation." (PMID 39351198, 2024). "Several known cancer and human MM driver genes were observed within focal GISTIC peaks, including homozygous deletions of Cdkn2a/b (7.3%), Rb1 (7.3%), and Pten (4%)." (PMID 38714690, 2024). "Many of these genes have previously been reported in cancer and also in the context of NB including NNAT, RB1, MAGEL2, GPR1, NDN." (PMID 39217334, 2024). "This article elucidates a new mechanism of anti-cancer surveillance mediated by the interplay between tumor suppressor proteins IFN-β and RB1." (PMID 37182173, 2023). "Among these, genes related to cell cycle progression (e.g., RB1, CDKN2A and CDKN2B), invasion and metastasis (e.g., CDH1 and CDH13) and apoptotic signaling (e.g., DAPK1) are hypermethylated in several cancers." (PMID 36866275, 2023). "As a result, there is a direct anti-cancer interaction between IFN-β signaling and RB1 function in the same cells." (PMID 37182173, 2023). "Abolishing Rb1 functionality thus leads to chromosomal instability (CIN), which further fuels cancer progression." (PMID 35267571, 2022). "High impact genes such as RB1 and BRCA1 are epigenetically inactivated at high frequencies which is why they were detected in the early days of molecular cancer research." (PMID 36084090, 2022). "On the other hand, a more recent study revealed that Rb1 binds p65 in response to CDK-mediated phosphorylation and inhibits its transcriptional activity specifically towards PD-L1, which confers cancer immune evasion." (PMID 35267571, 2022). "Data has shown that RB1 exists in S249/T252 in the form of CDK4/6 phosphorylation, which can counteract cancer immune evasion." (PMID 35299734, 2022). "Stathmin‐mediated disruption of microtubule dynamics is a key factor that induces the combined lethality of RB1‐deficient cancers and suggests that upstream factors that regulate microtubule dynamics, such as AURKA could be potential therapeutic targets for RB1‐deficient cancers." (PMID 34799997, 2022). "The loss control of the cell cycle induced by upregulated E2F1 in the HPV-positive group of CESC, HNSC, and UCEC and downregulated RB1 in the HPV-positive group of STAD played an important role on the formation and progression of the four cancers." (PMID 35392231, 2022).